ALX4 (ALX homeobox 4)
Description:
Transcription factor involved in skull and limb development. Plays an essential role in craniofacial development, skin and hair follicle development.
Synonyms: KIAA1788; FPP; PFM; CRS5; FND2; formerly PFM2
Tractability: No criterion of Open Targets' tractability assessment is met for any kind of drug.
Gene: Protein-coding gene on chromosome 11 (44,260,440 to 44,310,139, reverse strand). Ensembl gene ENSG00000052850.
Subcellular location: Nucleus
Subcellular location (Human Protein Atlas): Nucleoplasm
Gene Ontology:
Molecular function: protein binding; sequence-specific double-stranded DNA binding; DNA binding; DNA-binding transcription activator activity, RNA polymerase II-specific; DNA-binding transcription factor activity, RNA polymerase II-specific; RNA polymerase II transcription regulatory region sequence-specific DNA binding; DNA-binding transcription factor activity; HMG box domain binding; sequence-specific DNA binding
Biological process: hair follicle development; neuron development; regulation of transcription by RNA polymerase II; skeletal system development; animal organ development; positive regulation of transcription by RNA polymerase II; regulation of DNA-templated transcription
Cellular component: nucleoplasm; nucleus; chromatin; transcription regulator complex
Genetic constraint (gnomAD): Loss-of-function variants: 22 observed, 34.82 expected, observed/expected ratio (o/e) 0.63, 90% interval 0.45 to 0.9. The upper end of that interval is the gene's LOEUF score, 0.9, which puts it in group 3 of 6, group 1 being the genes least tolerant of losing a copy. Missense variants: 556 observed, 539.32 expected, observed/expected ratio (o/e) 1.03, 90% interval 0.96 to 1.11. Synonymous variants: 266 observed, 233.9 expected, observed/expected ratio (o/e) 1.14, 90% interval 1.03 to 1.26.
Gene-disease validity (ClinGen):
ClinGen rates the evidence that ALX4 causes each of these diseases.
frontonasal dysplasia with alopecia and genital anomaly (autosomal recessive): Definitive. Frontonasal dysplasia with alopecia and genital anomaly is a new phenotype of frontonasal dysplasia associated with total alopecia and hypogonadism.
Homologues: Orthologues: chimpanzee ALX4 (99% identical), macaque ALX4 (99% identical), pig ALX4 (94% identical), dog ALX4 (94% identical), rabbit ALX4 (91% identical), mouse Alx4 (90% identical), rat Alx4 (90% identical), guinea pig ALX4 (89% identical), tropical clawed frog alx4 (65% identical), zebrafish alx4a (62% identical), zebrafish alx4b (56% identical), zebrafish alx3 (11% identical). Paralogues in human: ALX1 (33% identical), ALX3 (32% identical), ARX (27% identical), VSX2 (24% identical), UNCX (22% identical), RAX (22% identical), DMBX1 (21% identical), PAX7 (20% identical), PITX2 (19% identical), PRRX2 (19% identical), PAX3 (19% identical), OTP (19% identical), and 38 more.
Diseases named in the same sentence as ALX4 in open-access papers:
ALX4 is named in the same sentence as 68 diseases in open-access papers, as found by Europe PMC text mining. Sharing a sentence is not in itself a finding about the gene and the disease. The quoted sentences say what the papers report.
breast carcinoma (8 papers, 2017 to 2025). "To further confirm these results, we performed a meta-analysis of the association between ALX4 gene expression and prognostic outcomes among 1080 breast cancer patients using the TCGA data base." (PMID 29183346, 2017). "Taken together our data showed that ALX4 is an independent favorable prognostic factor for breast cancer patients and its expression is associated with clinical parameters." (PMID 29183346, 2017). "miR-1299 was able to inhibit GLUT1 expression, but miR-1299 levels were downregulated by circ_0001955, resulting in increased GLUT1 levels.The transcription factor ALX4 is a tumor suppressor that plays an important inhibitory role in breast cancer development." (PMID 37204526, 2023). "To confirm our findings from the in vitro assays, we next examined the effect of overexpression of ALX4 or WDR86 on breast cancer cell growth in a xenograft model in vivo." (PMID 32539762, 2020). "Knockdown of two upregulated genes (DYNLT3 and P4HA3) or overexpression of the downregulated ALX4 significantly reduced breast cancer cell proliferation, migration, and clonogenicity." (PMID 32539762, 2020). "On the other side, we showed that overexpression of ALX4, a potential tumor suppressor, significantly inhibited the malignant properties of breast cancer cells." (PMID 32539762, 2020). "These published studies together with ours support the conclusion that ALX4 acts as a putative tumor suppressor in subsets of breast cancer." (PMID 32539762, 2020). "Specifically, the upregulation of DYNLT3 and P4HA3 as well as the downregulation of ALX4 during aging promote breast cancer progression." (PMID 32539762, 2020). "As we were completing our experiments involving ALX4, Yang and co-workers also reported the tumor-suppressive function of ALX4 in breast cancer cells." (PMID 32539762, 2020). "The expression of ALX4 in breast cancer cell lines and patients’ tissues were detected by RT-PCR, qPCR and western blot." (PMID 29183346, 2017). "Functional studies showed that ectopic expression of ALX4 in breast cancer cells inhibited cell proliferation, metastasis in vitro and in vivo." (PMID 29183346, 2017). "The results showed that ALX4 was down regulated in breast cancer cell lines compared with the normal breast tissues both on mRNA and protein level." (PMID 29183346, 2017). "We reveal for the first time that ALX4 acts as a novel functional tumor suppressor inactivated by DNA methylation and is an independent prognostic factor in breast cancer." (PMID 29183346, 2017). "Collectively, these data indicated that ALX4 had a significant effect on impeding tumor formation and metastasis, supporting ALX4 as a tumor suppressor in breast cancer in vivo." (PMID 29183346, 2017). "Previous study found that ALX4 promoted ovarian cancer invasion by forming a complex with HOXB13 but our data showed that ALX4 inhibited breast cancer metastasis." (PMID 29183346, 2017). "Consistent with our results, ALX4 expression was down regulated in TCGA breast cancer tissues compared with normal breast tissues (P < 0.01)." (PMID 29183346, 2017). "We further examined the methylation of clinical samples and the results showed that the methylation rate of the promoter region of ALX4 gene was 69.44% (75/108) in breast cancer tissues of patients, and 0% (0/8) in 8 normal breast tissues." (PMID 29183346, 2017). "The expression status of ALX4 in breast cancer cell lines and normal breast tissues were detected by RT-PCR, qRT-PCR and WB." (PMID 29183346, 2017). "In summary, our study indicates for the first time that ALX4 is an epigenetically inactivated tumor suppressor in breast cancer acting through inhibition the Wnt/β-catenin pathway." (PMID 29183346, 2017). "In the present study we detected the expression and promoter methylation status of ALX4 in breast cancer cell lines, normal human breast tissues and primary human breast tumor tissues." (PMID 29183346, 2017).
breast carcinoma (continued). "In vitro proliferation, metastasis and in vivo nude mice model were used to evaluate the anti-tumor effect of ALX4 on breast cancer cell lines." (PMID 29183346, 2017). "MSP study showed that the promoter region of ALX4 was hyper-methylated 100% (3/3) in breast cancer cell lines and 69.44% (75/108) in primary breast tumors tissues while 0% (0/8) in normal breast tissues." (PMID 29183346, 2017). "We found that ALX4 expression is an independent favorable prognostic factor and is in tight relationship with clinical stages, tumor size and lymph node status in breast cancer patients." (PMID 29183346, 2017). "Expression analysis revealed that ALX4 expression is down regulated in breast cancer cell lines and tissues." (PMID 29183346, 2017). "Taken together our results supported that ALX4 inhibited the progression of breast cancer through interfering Wnt/β-catenin signaling via promoting phosphorylation degradation of β-catenin in a GSK3β dependent manner." (PMID 29183346, 2017). "We further determined the possible mechanisms of the tumor inhibition effect of ALX4 in breast cancer." (PMID 29183346, 2017). "Clinically multivariate analysis showed that ALX4 expression was an independent favorable prognostic factor in breast cancer patients." (PMID 29183346, 2017). "In breast carcinoma, ALX4 has been shown to be a downregulated epigenetic tumor suppressor gene that could also inhibit the progression of breast cancer via the Wnt/β‐catenin pathway." (PMID 35023304, 2022). "Interestingly, E4 predominantly upregulated ALX4, a tumor suppressor transcription factor downregulated in breast cancer cell lines such as MCF7 and in 70% of breast cancer from patients." (PMID 34065180, 2021). "Moreover, knockdown of P4HA3 reduced growth and metastasis whereas overexpression of ALX4 inhibited the growth of xenografted breast cancer cells in mice." (PMID 32539762, 2020). "Meanwhile, ALX4 inhibited breast cancer cell proliferation and metastasis." (PMID 32650755, 2020). "DYNLT3, P4HA3, and ALX4 play significant roles in breast cancer progression." (PMID 32539762, 2020). "In the present study we firstly showed that ALX4 was down regulated in breast cancer." (PMID 29183346, 2017). "Furthermore, by analyzing the TCGA breast cancer data, we found that the expression of ALX4 was positively correlated with the expression of the key members of the “β-catenin degradation complex”." (PMID 29183346, 2017). "Furthermore the expression of ALX4 is an independent favorable prognostic factor in breast cancer patients and is in tightly relationship with tumor progression." (PMID 29183346, 2017). "In addition to tumor size (HR = 1.268, P = 0.00), ALX4 expression was found to be an independent prognostic factor (HR = 0.345, P = 0.01) for the overall survival of breast cancer patients." (PMID 29183346, 2017). "Thus gain and loss of function studies were carried out to examine the function of ALX4 in breast cancer." (PMID 29183346, 2017). "Furthermore the biological function, molecular mechanisms and clinical significance of ALX4 were investigated in breast cancer." (PMID 29183346, 2017). "We found that ectopic expression of ALX4 could inhibit the canonical Wnt signaling activity in breast cancer by TOP/FOP flash reporter assay and the Wnt target functional genes MMP7, c-Myc and Cyclin D1 were down regulated both at protein and mRNA level." (PMID 29183346, 2017). "Furthermore, we investigated the effect of ALX4 over expression on breast cancer cells metastasis in vivo via tail veins injection method." (PMID 29183346, 2017). "Therefore, to evaluate the clinical significance of ALX4 in breast cancer patient, we performed a tissue microarray on 142 breast cancer patients with clinical and survival data." (PMID 29183346, 2017).
breast carcinoma (continued). "Distance invasiveness is another malignant phenotype which contributes to the high mortality of breast cancer and we found that ALX4 could attenuate the metastasis ability of breast cancer cell lines in vitro and in vivo." (PMID 29183346, 2017). "5-aza-dc de-methylation treatment restored ALX4 expression in breast cancer cell lines." (PMID 29183346, 2017). "We further investigated the effect of ALX4 on breast cancer cell metastasis." (PMID 29183346, 2017). "We next went to explore the possible mechanism by which ALX4 suppressed breast cancer progression." (PMID 29183346, 2017). "Furthermore, we found that ALX4 over expression induced G1 / S blockade of breast cancer cell lines." (PMID 29183346, 2017). "Collectively these results suggested that ALX4 was down regulated in breast cancer, thus it may play an important role in breast cancer development." (PMID 29183346, 2017). "Using MSP and BSP methods we found that the promoter region of ALX4 was frequently methylated in breast cancer and demethylation treatment could recover the expression of ALX4." (PMID 29183346, 2017). "Interestingly, eight genes (ID4, LTBP4, GPM6B, RGMA, EFCAB1, ALX4, OSR1 and PPARA) were confirmed to be down-expressed in breast cancer tissues, and associated with the overall survival time of breast cancer patients, as high expression of these genes correlate with an improved prognosis." (PMID 32650755, 2020). "We further investigated the relationship between ALX4 expression and clinical parameters, and found that ALX4 expression was evidently correlated to clinical stages (n = 140, P = 0.01), tumor size (n = 142, P = 0.01) and lymph node status (n = 138, P = 0.00) of breast cancer patients." (PMID 29183346, 2017). "These evidences indicted that ALX4 may be involved in the tumorigenesis of breast cancer." (PMID 29183346, 2017). "ALX4 is a paired-like homedomain transcription factor mainly expressed in the mesenchymal compartment of variety of developing tissues, but its functions, regulation mechanisms and clinical values in breast cancer remains unclear." (PMID 29183346, 2017). "CircKLHL24 can inhibit the proliferation and migration of breast cancer cells, downregulate the levels of HK2, GLUT1 and LDHA, and upregulate the expression of ALX4 by competitively binding miR-1204, thereby achieving tumor inhibition." (PMID 37204526, 2023). "The potential target genes of miR-1908-3p in breast cancer included ID4, LTBP4, GPM6B, RGMA, EFCAB1, ALX4, OSR1 and PPARA." (PMID 32650755, 2020). "To test the function of the two downregulated ABC genes, ALX4 and WDR86, we ectopically introduced their cDNA via a lentiviral vector to increase their expression in the breast cancer cell lines." (PMID 32539762, 2020). "Previous mice model study demonstrated that ALX4 is required for normal mammary gland morphogenesis during mouse puberty and lost expression in stromal and epithelial cells in breast tumors, suggesting it may be involved in the precancerous lesions of breast cancer." (PMID 29183346, 2017). "To investigate the function of ALX4 in breast cancer, we first transfected MDA-MB-231 and MCF-7 cell lines using control vector and ALX4 expression vector and verified the expression of ALX4 by WB and RT-PCR." (PMID 29183346, 2017). "To investigate the clinical significance of ALX4 expression in breast cancer patients, we first conducted IHC on a TMA containing 142 breast cancer patients with overall survival clinical statistics." (PMID 29183346, 2017). "For example, aristaless-like homeobox 4 (ALX4) is a pro-apoptotic tumor suppressor that negatively regulates proliferation, colony formation, epithelial-to-mesenchymal transition (EMT), and invasion in hepatocellular, colorectal, lung, and breast carcinomas." (PMID 41066027, 2025).
breast carcinoma (continued). "Based on these findings, a potential miR-1908-3p-mRNA regulatory network, miR-1908-3P-ID4/ LTBP4/ GPM6B/ RGMA/ EFCAB1/ ALX4/ OSR1/ PPARA, contributing to breast cancer onset and progression could be established." (PMID 32650755, 2020). "Ectopic expression of ALX4 induced apoptosis (data not shown) and G1/S blocking thus inhibited the proliferation of breast cancer cells in vitro." (PMID 29183346, 2017). "However, luciferase reporter assay showed that ALX4 had no significant inhibition effects on the transcription of β-catenin in the two breast cancer cell lines." (PMID 29183346, 2017).
colorectal cancer (8 papers, 2010 to 2025). A primary or metastatic malignant neoplasm that affects the colon or rectum. "Hypermethylation of the ALX4 gene was associated with tumorigenesis and prognosis in colorectal cancer." (PMID 25944620, 2015). "The method identified 7,091 hypermethylated markers, including ALX4 which showed progressive increases with colorectal cancer stage." (PMID 41258415, 2025). "It has been reported that there was a significant difference of ALX4 methylation status between a sample of Iranian colorectal cancer patients and controls which introduced that as an efficient marker for the early detection of colorectal cancer in this population." (PMID 33883026, 2021). "Notably, several genes such as ALX4, CHD5, MYOD1, NEUROG1, and RASSF5, whose methylation profile distinguishes this group of HCC patients from the other HCC patients, were previously reported to be similarly hypermethylated and associated with poor prognosis in colorectal cancer." (PMID 25093504, 2014). "Previously we independently detected a significant higher prevalence of methylated ALX4 and SEPT9 DNA in peripheral blood of colorectal cancer patients compared to controls." (PMID 20140221, 2010).
craniosynostosis (5 papers, 2022 to 2024). Craniosynostosis is defined as the premature fusion of one or more cranial sutures leading to secondary distortion of skull shape resulting in skull deformities with a variable presentation. "Genetic variants of ALX4 have been linked to craniosynostosis across multiple studies." (PMID 36982425, 2023). "FND2, which is characterized by craniosynostosis, cranium bifidum, and brain abnormalities, is a result of ALX4 mutations." (PMID 38673496, 2024). "Though ALX4 was not differentially expressed between cases and controls in our study, ALX1 was significantly increased in metopic craniosynostosis in our primary and male-stratified models." (PMID 36982425, 2023).
frontonasal dysplasia (4 papers, 2012 to 2024). A group of rare bone development disorders characterized by an array of abnormalities affecting the eyes, forehead, and nose, and linked to midfacial dysraphia. "Mutations in genes encoding the ALX homeodomain-containing transcription factors (ALX1, ALX3 and ALX4) are associated with frontonasal dysplasia and produce midfacial phenotypes in vertebrate species." (PMID 38063857, 2024). "Given the spectrum of human midfacial anomalies associated with disrupted functions of TFAP2A (branchio-oculo-facial syndrome), TFAP2B (Char syndrome), and ALX1, ALX3 and ALX4 (frontonasal dysplasia), these findings link features of previously disparate disorders into a shared genetic hierarchy." (PMID 38063857, 2024). "Frontonasal dysplasia resulted from ALX1, ALX3, ALX4 can also present bifid nose." (PMID 38097983, 2023).
Intellectual disability (4 papers, 2013 to 2022). "Clinical cardinal features of PSS syndrome are multiple exostoses (due to the EXT2 involvement), biparietal foramina (due to the ALX4 involvement), intellectual disability, and craniofacial anomalies (due to the PHF21A involvement)." (PMID 36555772, 2022). "Patients with a deletion involving ALX4, ELX2, and PHF21A genes had the cardinal PSS features: biparietal foramina, multiple exostosis, and intellectual disability and craniofacial anomalies associated with ALX4, ELX2, and PHF21A, respectively." (PMID 33126574, 2020). "Current literature implies a minimal region with haploinsufficiency of three genes, ALX4 (parietal foramina), EXT2 (multiple exostoses), and PHF21A (craniofacial anomalies, and intellectual disability)." (PMID 33126574, 2020).